LINC01324 (long independently transcribed non-coding RNA 1324)
Synonyms: LINC01323; TCONS_00005874
Gene: Long non-coding RNA gene on chromosome 3 (164,670,878 to 164,904,916, reverse strand). Ensembl gene ENSG00000241767.
Diseases named in the same sentence as LINC01324 in open-access papers:
LINC01324 is named in the same sentence as 1 disease in open-access papers, as found by Europe PMC text mining. Sharing a sentence is not in itself a finding about the gene and the disease. The quoted sentences say what the papers report.
cancer (1 paper, 2023). A tumor composed of atypical neoplastic, often pleomorphic cells that invade other tissues. "Among which three genes, EXOC6 (Padj|ESCC=7.30×10-3, Padj|GC=6.00×10-4, Padj|CRC=2.6×10-2), LRP5L (Padj|ESCC=2.70×10-3, Padj|GC=5.70×10-3, Padj|CRC=1.65×10-2), MIR1263/LINC01324(Padj|ESCC=3.22×10-2, Padj|GC=4.36×10-2, Padj|CRC=3.26×10-2) were statistically significant in all three cancer types." (PMID 37483484, 2023).